CAV1 (caveolin 1)
Diseases named in the same sentence as CAV1 in open-access papers (continued):
Sharing a sentence is not in itself a finding about the gene and the disease.
breast carcinoma (continued). "The 5’ region of the caveolin-1 promoter is enriched in CpG islands that are not methylated in normal breast epithelial cells and express higher levels of CAV1; however, in breast cancer cell lines that do not express CAV1, this region is highly methylated." (PMID 29340103, 2017). "Knockdown of Cav-1 resulted in slight inhibition in LSS-induced cell motility, which also suggests that Cav-1 may act in breast cancer metastasis." (PMID 26919102, 2016). "Immunohistochemical studies of human breast cancer specimens revealed that biopsies lacking stroma Cav-1 overexpressed key glycolytic enzymes, such as PKM2 and LDH." (PMID 26431273, 2015). "It is suggested that the 5′ promoter of CAV1 is methylated in human breast cancer cell lines, MDA-MB-231, MCF7 and T-47D but not in normal human mammary epithelial cells." (PMID 26112043, 2015). "Meanwhile, transcriptional profiles of Cav-1-negative (−) tumor stroma revealed up-regulation of 238 genes and downregulation of 232 genes compared to Cav-1 positive (+) breast cancer stroma." (PMID 26431273, 2015). "Meta-analysis from 19 eligible studies included a total of 5,926 patients with a median number of 312 patients per study failed to recognize that caveolin-1 expression in tumor cells as a predictive marker for breast cancer prognosis." (PMID 26172389, 2015). "However, in a subtype of breast cancer, inflammatory breast cancer (IBC), CAV1 is reported to be hypomethylated resulting in overexpression of CAV1." (PMID 26112043, 2015). "Also, MCF7 breast cancer cells that express caveolin-1 demonstrate much higher levels of IGF-IR gene promoter activity, and the effects of caveolin-1 on the IGF-IR gene promoter were mediated through Sp1." (PMID 25884514, 2015). "For example, expression of CAV1, CAV2 and PTRF is dysregulated in prostate and breast cancer." (PMID 26112043, 2015). "Both proteins are predominantly located in the Lubrol-based detergent-insoluble glycosphingolipid-enriched membrane domains and co-immunoprecipitation assays confirm that Cav-1 interacts with ABCB1 in brain capillaries, rat brain endothelial, Chinese hamster ovary and breast cancer cells." (PMID 26431273, 2015). "In the present study, we showed that c-Src dependent Caveolin-1 phosphorylation promoted the translocation of P-gp into caveolae, resulting in multidrug resistance in adriamycin resistant gastric cancer SGC7901/Adr and breast cancer MCF-7/Adr cells." (PMID 25788263, 2015). "Conversely, up-regulated caveolin-1 suppressed function and surface expression of BKCa channel and exerted negative effects on breast cancer cell proliferation and invasion." (PMID 25397596, 2014). "Conversely, inhibition of BKCa channel by caveolin-1 up-regulation exerted negative effects on breast cancer cell proliferation and invasion." (PMID 25397596, 2014). "Conversely, up-regulated caveolin-1 suppressed function and surface expression of BKCa channels and exerted negative effects on breast cancer cell proliferation and invasion." (PMID 25397596, 2014). "The absence of stromal Cav1 has been reported to predict early tumour recurrence and lymph node metastases and to be a predictor of poor clinical outcome in breast cancer." (PMID 23521716, 2013). "Consistent with the resultof earlier studies, knockdown of PLU1 reduced MCF7 breast cancer cellproliferation and concomitantly upregulated expression of the Breastcancer1, early onset (BRCA1), Caveolin 1(CAV1), and HOXA5 genes as a result of increasedH3K4me3 levels on their promoters." (PMID 24172249, 2013). "Survival analysis indicates that the absence of fibroblastic Cav-1 expression is a powerful independent predictor of early disease recurrence, metastasis and adverse outcome in breast cancer, confirming its tumor-promoting role." (PMID 23203033, 2012).
breast carcinoma (continued). "Cell line models of HER2-positive breast cancer that had acquired resistance to lapatinib or to lapatinib plus trastuzumab showed increased expression of ER or a downstream target of ER (progesterone receptor, IGF-IR, Cav-1)." (PMID 23227361, 2012). "This caveolin-1 expression pattern was maintained in the murine mammary tumor cell lines in that the epithelial mammary tumor cell lines expressed little or no caveolin-1 while the claudin-low cell lines expressed caveolin-1." (PMID 22356861, 2012). "In contrast, IGF-IR independent mammary tumors and the murine mammary tumor cell lines RJ348 and RM11A that expressed very low levels of E-cadherin and had gene expression patterns similar to claudin-low tumors also expressed considerable amounts of Cav-1." (PMID 22356861, 2012). "Our study confirmed that mRNA level of CAV1 and CAV2 were significantly downregulated in human breast cancer tissues compared to corresponding normal tissues (P<0.001), and that CAV1 and CAV2 mRNA levels were significantly correlated with each other in breast cancer cell lines and tissues." (PMID 15305200, 2004). "However, to our knowledge, there are no studies on the relationship between CAV1 genotypes and prognosis in breast cancer." (PMID 37017811, 2023). "No studies have examined the levels of Cav1 in terms of breast cancer disparities." (PMID 37822942, 2023). "Some researchers support the first view because low or absent levels of Cav-1 mRNA and protein can be seen in tumor tissue samples from human primary breast cancer patients, oncogene-transformed cells, transgenic mouse breast cancer models, and some human or mouse transformed epithelial cell lines." (PMID 37828916, 2023). "The integral membrane protein caveolin-1 was identified as an important factor in spheroid formation of thyroid cancer cells in an μg environment which further inhibits anchorage-independent growth and anoikis, obviously two independent processes, in MCF-7 breast cancer cells." (PMID 32033410, 2020). "Also, in vitro exposure of breast cancer cells lacking CAV1 to EVs containing CAV1 increased their migration and invasiveness as compared to recipient cells of EVs derived from MDA-MB-231 cells in which CAV1 was silenced." (PMID 32458269, 2020). "However, HIF1α protein levels induced by hypoxia were neither affected by CAV1 overexpression in HT29(US) colon cancer cells or by CAV1 knockdown in the breast cancer cell line MDA-MB-231." (PMID 32825247, 2020). "Alternatively, in metastatic colon, breast cancer, and melanoma cells (lacking E-cadherin), CAV1 does not polarize during migration and presence of the protein following Y14 phosphorylation is associated with activation of a novel CAV1-Rab5-Rac1 signaling axis." (PMID 31362353, 2019). "Maybe these 4 breast cancers were not basal-like subtype or the difference of Cav-1 expression between subtypes mainly came from HER2-positive breast cancer." (PMID 30348118, 2018). "For breast cancer cases, similar to gastric cancer, characteristic proteins are ASNS and Cyclin_B1, whereas for cases similar to thyroid carcinoma, characteristic proteins with increased expression are Caveolin-1, Collagen_VI, PR, MAPK_pT202_Y204, and ER-alpha." (PMID 30442178, 2018). "If caveolin-1 acts as a pro-invasive switch combined downregulation of caveolin-1 and FASN/ERα signalling might be necessary to effectively suppress cell growth and prevent invasion in a specific subset of ERα-positive breast cancer patients." (PMID 29331414, 2018). "Other studies have suggested that CAV1 plays a negative role in breast cancer." (PMID 29190968, 2017).
breast carcinoma (continued). "The analysis of available data also indicated that the expression level of Cav-1 and MnSOD in human breast cancer has weak negative prognostic value independently, but in combination, the Cav-1low/MnSODhigh signature is strongly correlated with more aggressive forms of the disease." (PMID 26543228, 2016). "Moreover, considering previous reports that EGFR signaling is attenuated by cav-1 overexpression in senescent cells and breast cancer, attenuated EGFR signaling shown in parkin KO mouse brain is speculated to be partially mediated by the accumulation of cav-1." (PMID 26627850, 2015). "In addition, in the study of Western blot protein evaluation, 8 (72.72%) of the 11 HER-2 positive breast cancer patients were found to have a high expression of caveolin-1 in tumor tissue than in the non-tumor part of the patient." (PMID 26172389, 2015). "Whether a functional interaction between caveolin-1 and BKCa exists in breast cancer cells and its impacts on cell malignancy are not known." (PMID 25397596, 2014). "Previous studies have not reached a consensus concerning the role of Cav-1 in human breast cancer." (PMID 25202343, 2014). "It is already clear that the expression state of stromal Cav-1 is coincidently downregulated in various types of human cancer, including breast cancer, compared with non-cancerous tissues, and the mechanisms and clinical role of the deregulation of Cav-1 have been sufficiently demonstrated." (PMID 25202343, 2014). "Overall, this clinicopathological study of breast cancer revealed a significant correlation between the absence of stromal Cav-1, and larger tumor size, advanced tumor stage (TNM stage), higher grade, lymph node metastasis, poor tumor prognosis and short overall survival time." (PMID 25202343, 2014). "In a few tumors where fibroblasts could be found adjacent to the mammary tumor, these fibroblasts displayed little or no staining for Cav-1." (PMID 22356861, 2012). "Most of the epithelial cells of the mammary tumors expressed little or no Cav-1 protein." (PMID 22356861, 2012). "Therefore, CAV1 and CAV2 play an important role in tumour progression in breast cancer patients." (PMID 15305200, 2004). "Specifically, potassium channel activation-dependent Cav-1 dephosphorylation was observed in highly metastatic breast cancer cells, suggesting that targeting this pathway could be a novel therapeutic approach to inhibit cancer cell migration and enhance contact inhibition." (PMID 40358155, 2025). "Additionally, using in vivo models, downregulation of CAV1 in breast-cancer stem cells also effectively impaired the tumorigenicity and chemoresistance, highlighting the importance of the CAV1-regulated β-catenin/ABCG2 signaling axis in chemoresistance of breast-cancer stem cells." (PMID 35158857, 2022). "Similarly, BCSCs isolated from mammary tumors of MMTV-Wnt1 mice also exhibited elevated glycolytic activity and decreased mitochondrial membrane potential when compared with NBSCs isolated from wild type mice, which was accompanied by decreased expression of Cav-1 but increased expression of c-Myc." (PMID 32528105, 2020). "Given that Cav-1−/− mice could not generate mammary tumors spontaneously, to further investigate the influence of Cav-1 on mice mammary-tumor formation in vivo, MMTV-Wnt1/Cav-1+/− tumor-prone mice were generated by crossbreeding male MMTV-Wnt1 mice with female Cav-1−/− mice." (PMID 32528105, 2020). "The co-culture of human breast cancer cells (MCF7) and immortalized fibroblasts (hTERT-BJ1) or normal human mammary fibroblasts leads to autophagic/lysosomal degradation and down regulation of Cav-1 in fibroblasts, resulting in cancer associated fibroblast (CAFs) phenotype." (PMID 31759347, 2019).
breast carcinoma (continued). "Similarly, members of the mir-17/92 cluster and paralog clusters were predicted by our sequence complementarity components to co-regulate three different transcripts of CAV1, whose role in breast cancer has been extensively studied but had not been previously linked to miR-17/92." (PMID 27213017, 2016). "Those latter studies showed that breast cancer cells were able to induce oxidative stress (via a yet unknown mechanism) and/or hypoxic conditions (via HIF-α) in CAFs, which, in turn, activated autophagic and lysosomal degradation of CAV1 as well as of dysfunctional mitochondria." (PMID 25633184, 2015). "However, the clinical significance of CAV1 in breast cancer has not yet been clarified." (PMID 15305200, 2004). "CAV1 and CAV2 also elucidated independent predicting value in the RFS of ER+ breast cancer patients, but the prognosis of breast cancer patients with other receptor status was not well differentiated by expression levels of CAV1 and CAV2." (PMID 34513683, 2021). "Among the multiple breast cancer cell lines tested, ZR75–1, SKBR3, and MCF7 had no or low CAV1 expression, whereas MDA-MB-231 and MDA-MB-436 had strong CAV1 expression." (PMID 30333750, 2018). "Conversely, in previous studies we observed during 2D migration of metastatic breast cancer (MDA-MB-231) and melanoma (B16F10) cells that polarization of CAV1 was not required, although presence of the protein clearly favors migration." (PMID 27259249, 2016). "However, whether caveolin-1 interacts with BKCa in breast cancer cells is not known." (PMID 25397596, 2014). "Compilation of data obtained on the same breast cancer tissue microarray probed with antibodies to gp78/AMFR and Cav1 shows that gp78/AMFR and Cav1 tumor cohorts do not correlate with one another (p = 0.421)." (PMID 18974847, 2008). "In addition, the possible ferroptosis mechanisms of CDKN2A, PSAT1, SLC7A11, LAMP2, CAV1, and HMGB1 in TNBC and ASNS, ZFP69B, ELAVL1, TF, HELLS, and DPP4 in breast cancer have not been reported." (PMID 36568247, 2022). "We previously showed that gp78/AMFR expression was elevated in metastatic MDA-435 and MDA-231 cells relative to non-metastatic MCF-7 and dysplastic MCF10A mammary tumor cells and that AMF/PGI-FITC uptake was selectively increased in MDA-435 cells that express reduced levels of Cav1." (PMID 18974847, 2008). "Much higher protein levels of caveolin-1 were also observed in the highly invasive ERα-negative MDA-MB-231 and Hs578T cells when compared to the non-metastatic ERα-positive MCF-7 and T47D cells, indicating a strong correlation between caveolin-1 expression and breast cancer aggressiveness." (PMID 29331414, 2018). "In CAV1high MDA-MB-231 cells, CAV1 knockdown did not significantly aggravate the inhibitory ability of ADQ in the presence of paclitaxel, suggesting that ADQ might target CAV1 to chemosensitize breast cancer." (PMID 30333750, 2018).
prostate carcinoma (177 papers, 2002 to 2025). A carcinoma that arises from epithelial cells of the prostate gland. "In glioma and prostate cancer, CAV1 has been implicated as a perquisite for maintaining tumor stemness, where it is known to have a regulatory role in platelet-derived growth factor signaling." (PMID 38959243, 2024). "Biologically, we attributed increases in circulating sphingolipids to an underlying onco-metabolic pathway that is active in prostate cancer cells and that is regulated by Cav1." (PMID 39522029, 2024). "CAV1 plays a central role in radioresistance‐mediated tumour‐stroma interactions in advanced prostate cancer (PCa), CAV1‐deficient endothelial cells increased growth delay of PCa cell after radiation treatment." (PMID 38158643, 2024). "This article reviews the structure, physiological and pathological functions of Cav1, the pathogenic signaling pathways involved in prostate cancer, and the current drug treatment of prostate cancer." (PMID 37910338, 2023). "Enhanced expression of Cav1 in prostate cancer has been linked to both proliferation and metastasis of cancer cells, influencing disease progression." (PMID 37910338, 2023). "In another study, elevated level of caveolin-1 in prostate cancer tumor vasculature has been linked to radio-resistance in MPR31-4 prostate cancer xenograft tumors, and its knock down reversed radio-resistance in those animals." (PMID 34762666, 2021). "Recently, cellular RNA from stromal cells has been shown to predict metastatic prostate cancer, and decreased mRNA expression of Caveolin‐1 (CAV1) within tumour‐associated stroma was linked to poor prognosis." (PMID 34596356, 2021). "The overexpression of Cav-1 seems to be associated with low degree of differentiation, advanced clinical stage, and poor survival in prostate cancers." (PMID 34590611, 2021). "For instance, Cav1 influences Wnt/β-catenin signaling in prostate cancer, and in Cav1-deficient stem cells Wnt signaling is upregulated." (PMID 34769308, 2021). "We have also previously demonstrated the increased plasma Cav-1 to be associated with early disease reclassification in individuals with prostate cancer that initially present with clinically localized disease." (PMID 32855410, 2020). "The mechanisms associated with Caveolin-1 (Cav-1) mediated metabolic changes in prostate cancer are unclear." (PMID 32855410, 2020). "In summary, we have specified the role of CAV1 alterations potentially induced by CAV1-deficient and more reactive, stroma in radio sensitivity of prostate carcinoma at molecular level." (PMID 30871022, 2019). "The role of scaffolds is less well-characterized, in large part due to difficulties distinguishing these two Cav1-positive membrane domains, but they have been specifically associated with regulation of receptor signaling and prostate cancer progression." (PMID 31449531, 2019). "In conclusion, we have determined the role of CAV1 alterations potentially induced by the CAV1-deficient, and more reactive, stroma in radio sensitivity of prostate carcinoma at a molecular level." (PMID 30871022, 2019). "We then investigated if the induced resistance of prostate cancer cells, after treatment with supernatants derived from CAV1-proficient or -deficient fibroblasts, led to higher TRIAP1 levels (not shown)." (PMID 30871022, 2019). "Loss of stromal CAV1 can even be used as a prognostic marker, for example, in breast and prostate cancer patients." (PMID 30871022, 2019). "Caveolin-1 (CAV1) is over-expressed in prostate cancer (PCa) and is associated with adverse prognosis, but the molecular mechanisms linking CAV1 expression to disease progression are poorly understood." (PMID 29402961, 2018). "Increased transcription of ABCA1 was associated with CAV‐1 stabilization in prostate cancer‐derived cells." (PMID 30098223, 2018).